WDFY3 (WD repeat and FYVE domain containing 3)
Description:
Required for selective macroautophagy (aggrephagy). Acts as an adapter protein by linking specific proteins destined for degradation to the core autophagic machinery members, such as the ATG5-ATG12-ATG16L E3-like ligase, SQSTM1 and LC3. Along with p62/SQSTM1, involved in the formation and autophagic degradation of cytoplasmic ubiquitin-containing inclusions (p62 bodies, ALIS/aggresome-like induced structures). Along with SQSTM1, required to recruit ubiquitinated proteins to PML bodies in the nucleus. Important for normal brain development. Essential for the formation of axonal tracts throughout the brain and spinal cord, including the formation of the major forebrain commissures. Involved in the ability of neural cells to respond to guidance cues. Required for cortical neurons to respond to the trophic effects of netrin-1/NTN1 (By similarity). Regulates Wnt signaling through the removal of DVL3 aggregates, likely in an autophagy-dependent manner. This process may be important for the determination of brain size during embryonic development. May regulate osteoclastogenesis by acting on the TNFSF11/RANKL - TRAF6 pathway (By similarity). After cytokinetic abscission, involved in midbody remnant degradation. In vitro strongly binds to phosphatidylinositol 3-phosphate (PtdIns3P).
Synonyms: Alfy; KIAA0993; ZFYVE25; BCHS; MCPH18
Tractability: Antibody: UniProt places it where antibodies can reach, with high confidence; its Gene Ontology location is reachable by antibodies, with high confidence. PROTAC: ubiquitination databases record sites on it; its protein half-life has been measured.
Gene: Protein-coding gene on chromosome 4 (84,668,765 to 84,966,690, reverse strand). Ensembl gene ENSG00000163625.
Subcellular location: Nucleus membrane; Cytoplasm, cytosol; Nucleus, PML body; Membrane; Perikaryon; Cell projection, axon
Subcellular location (Human Protein Atlas): Cytosol; Nucleoli; Plasma membrane
Gene Ontology:
Molecular function: 1-phosphatidylinositol binding; protein binding; metal ion binding
Biological process: aggrephagy; macroautophagy
Cellular component: Atg12-Atg5-Atg16 complex; autophagosome; autophagosome membrane; cytoplasm; cytosol; inclusion body; membrane; nuclear envelope; nuclear membrane; PML body; axon; perikaryon
Genetic constraint (gnomAD): Loss-of-function variants: 62 observed, 382.53 expected, observed/expected ratio (o/e) 0.16, 90% interval 0.13 to 0.2. The upper end of that interval is the gene's LOEUF score, 0.2, which puts it in group 1 of 6, group 1 being the genes least tolerant of losing a copy. Missense variants: 2,961 observed, 4,352.3 expected, observed/expected ratio (o/e) 0.68, 90% interval 0.66 to 0.7. Synonymous variants: 1,487 observed, 1,564.5 expected, observed/expected ratio (o/e) 0.95, 90% interval 0.91 to 0.99.
Gene-disease validity (ClinGen):
ClinGen rates the evidence that WDFY3 causes each of these diseases.
syndromic intellectual disability (autosomal dominant): Definitive. A intellectual disability that is part of a larger syndrome.
Homologues: Orthologues: chimpanzee WDFY3 (99% identical), macaque WDFY3 (99% identical), dog WDFY3 (98% identical), rabbit WDFY3 (97% identical), pig WDFY3 (97% identical), mouse Wdfy3 (96% identical), guinea pig WDFY3 (96% identical), rat Wdfy3 (95% identical), tropical clawed frog wdfy3 (88% identical), zebrafish wdfy3 (84% identical), Drosophila melanogaster bchs (48% identical), Caenorhabditis elegans wdfy-3 (34% identical), and 1 more. Paralogues in human: WDFY4 (32% identical), LYST (18% identical), NBEAL2 (15% identical), NBEAL1 (15% identical), NBEA (13% identical), LRBA (13% identical), NSMAF (7% identical).